CCDC112 (coiled-coil domain containing 112)
Synonyms: MBC1; MGC39633
Tractability: Antibody: the Human Protein Atlas places it where antibodies can reach. PROTAC: ubiquitination databases record sites on it.
Gene: Protein-coding gene on chromosome 5 (115,267,190 to 115,296,756, reverse strand). Ensembl gene ENSG00000164221.
Subcellular location: Cytoplasm, cytoskeleton, microtubule organizing center, centrosome, centriolar satellite
Subcellular location (Human Protein Atlas): Cytosol; Plasma membrane; Nucleoplasm
Gene Ontology:
Molecular function: protein binding
Cellular component: centriolar satellite
Genetic constraint (gnomAD): Loss-of-function variants: 19 observed, 31.85 expected, observed/expected ratio (o/e) 0.6, 90% interval 0.41 to 0.88. The upper end of that interval is the gene's LOEUF score, 0.88, which puts it in group 3 of 6, group 1 being the genes least tolerant of losing a copy. Missense variants: 388 observed, 337.48 expected, observed/expected ratio (o/e) 1.15, 90% interval 1.06 to 1.25. Synonymous variants: 143 observed, 119.73 expected, observed/expected ratio (o/e) 1.19, 90% interval 1.04 to 1.37.
Homologues: Orthologues: chimpanzee CCDC112 (99% identical), macaque CCDC112 (98% identical), pig CCDC112 (90% identical), dog CCDC112 (87% identical), guinea pig CCDC112 (85% identical), rat Ccdc112 (85% identical), mouse Ccdc112 (85% identical), rabbit CCDC112 (78% identical). Paralogues in human: CCDC148 (17% identical).
Diseases named in the same sentence as CCDC112 in open-access papers:
CCDC112 is named in the same sentence as 7 diseases in open-access papers, as found by Europe PMC text mining. Sharing a sentence is not in itself a finding about the gene and the disease. The quoted sentences say what the papers report.
Astigmatism (1 paper, 2021). A type of refraction error associated with abnormal curvatures on the anterior and/or posterior surface of the cornea. "ELFN1 and CCDC112: Using trio analysis we identified two de novo missense variants in the ELFN1 and CCDC112 genes in patient T62 with SM (−3.6), delayed myelination, asymmetric cerebral hemispheres, epileptic encephalopathy, hypotonia, sensorineural hearing loss, myopia and astigmatism." (PMID 34946966, 2021).
tumor (3 papers, 2022 to 2023). "K-M curves showed that upregulated TRNP1, CCDC112, CFL1 were associated with poor OS) and CYB5D2, SLC22A1 were protective genes (expression of CYB5D2, SLC22A1 were decreased in tumor tissues, and higher expression of CYB5D2, SLC22A1 was associated with good OS)." (PMID 36881382, 2023). "Our analysis demonstrated that MYLK2, FAM83D, STC2, CCDC112, EPHX4 and MMP1 were differentially expressed between tumor and normal tissues, with higher expression in tumor tissues than in normal tissues (p < 0.0001)." (PMID 37309005, 2023).
CCDC112 also shares sentences with these, for which no sentence is quoted: Bc (1 paper); Epileptic encephalopathy (1); glioma (1); lymphoma (1); myopia (1).